SIRT1 (sirtuin 1)
Diseases named in the same sentence as SIRT1 in open-access papers (continued):
Sharing a sentence is not in itself a finding about the gene and the disease.
osteoporosis (continued). "Overall, our findings suggest that HGK possesses translational potential for the treatment of osteoporosis through SIRT1 activation." (PMID 42193234, 2026). "In SIRT1 heterozygous deficiency (SIRT1+/-) mice, we found that SIRT1 deficiency triggered SSPC ferroptosis and induced premature osteoporosis." (PMID 42193234, 2026). "HGK treatment effectively restored SIRT1 activity, suppressed ferroptosis in SSPCs in vitro, and ameliorated osteoporosis in vivo." (PMID 42193234, 2026). "Sirtuin 1 (SIRT1) is an important protein for maintaining cellular homeostasis, and targeting SIRT1 represents a promising strategy for alleviating osteoporosis." (PMID 42193234, 2026). "The results suggest resveratrol potentiates calcium’s bone protective effects in SCI-induced osteoporosis by modulating SIRT1/FOXO3a signaling and osteoblast/osteoclast activity, presenting a promising therapeutic approach." (PMID 41226117, 2025). "Resveratrol’s ability to modulate the SIRT1/β-catenin axis further emphasizes its potential as a therapeutic agent in combating osteoporosis and maintaining bone integrity during periods of hormonal decline." (PMID 40243497, 2025). "Clinically, reduced SIRT1 in adult femurs affects osteoporosis-related protein expression in the femoral neck and can lead to osteoporotic hip fractures." (PMID 40678144, 2025). "Therefore, our study indicates that in addition to conventional targeting of transcriptional Wnt/β-catenin signaling, the metabolic factor SIRT1 may represent a new target for the development of novel therapeutics aimed at preventing SMG-induced bone loss or treating patients with osteoporosis." (PMID 40004131, 2025). "Resveratrol enhances osteogenic differentiation in osteoporosis mice through the SIRT1/PI3K/AKT pathway, improving various bone parameters in vivo and in vitro." (PMID 40243497, 2025). "A 2025 study showed resveratrol enhances protective effects of calcium supplements against SCI-induced osteoporosis via the SIRT1/FOXO3a pathway regulating bone metabolism." (PMID 41226117, 2025). "Preclinical findings show that mice treated with SIRT1 activators have increased resistance to osteoporosis in models of aging and post-menopause." (PMID 40066121, 2024). "Logistic regression analysis highlighted that reduced SIRT1 levels, alongside age, HDL-C, P1NP, and β-CTX, were independent risk factors for osteoporosis in T2DM patients." (PMID 39944232, 2024). "Oxidative stress is an important factor in the pathogenesis of osteoporosis, and SIRT1 plays a key role in mitigating its effects." (PMID 39199358, 2024). "Stepwise binary logistic regression analysis further suggested that SIRT1, age, HDL-C, PINP, and β-CTX were independently associated with the pathogenesis of osteoporosis (P < 0.01 or P < 0.05)." (PMID 39944232, 2024). "In recent years, the potential of SIRT1 agonists in the treatment of osteoporosis has attracted much attention due to their ability to modulate key pathways in bone metabolism." (PMID 39199358, 2024). "The interactions between SIRT1 and other signaling pathways also play a key role in the pathogenesis of osteoporosis." (PMID 39199358, 2024). "Logistic regression indicated that Sirtuin 1, age, HDL-C, P1NP, and β-CTX were independent risk factors for osteoporosis in T2DM patients." (PMID 39944232, 2024). "The dual regulatory roles of SIRT1 in bone formation and bone resorption highlight its potential as a therapeutic target for the treatment of osteoporosis and other bone-related diseases." (PMID 39199358, 2024). "Subgroup analysis further reveals that T2DM patients with osteoporosis (DMo) have significantly lower serum Sirtuin 1 levels compared to those with normal bone mineral density (DMn)." (PMID 39944232, 2024). "Subgroup analysis revealed that SIRT1 levels in T2DM patients with osteoporosis or osteopenia exhibited a significant reduction compared to those with normal BMD (P < 0.05)." (PMID 39944232, 2024).
osteoporosis (continued). "In the control group, the fluorescence expression intensity of SIRT1 was suppressed in the bone tissue of the defect region, indicating the anti-oxidative stress ability of bone tissue decreased in osteoporosis." (PMID 39404912, 2024). "SIRT1 plays a key role in the pathogenesis of osteoporosis, particularly in postmenopausal women and the elderly." (PMID 39199358, 2024). "T2DM patients were further categorized into a normal BMD group (DMn) and an osteopenia or osteoporosis group (DMo), and differences in Sirtuin 1 levels between these subgroups were analyzed." (PMID 39944232, 2024). "SRT2104 is one of the latest synthetic SIRT1 activators that has been tested in animal models for age-related diseases including osteoporosis and Huntington’s disease." (PMID 38913048, 2024). "Several studies demonstrated that RSV treatment significantly increased the expression of SIRT-1 in osteoporosis rat model." (PMID 37239124, 2023). "Activation of SIRT1 can regulate the activity of osteoclasts and osteoblasts and improve bone metabolism, thereby reducing osteoporosis." (PMID 36632457, 2023). "SIRT1 activity in peripheral blood mononuclear cells was reduced concurrently, indicating a close relationship between SIRT1 and osteoporosis." (PMID 37239124, 2023). "This article reviews the impact of various aspects of mitochondrial quality control on osteoporosis, focusing on how SIRT1, SIRT3, and SIRT6 can improve osteoporosis by regulating mitochondrial protein homeostasis, biogenesis, and mitophagy." (PMID 38264287, 2023). "A clinical investigation found that the expression of SIRT1 was considerably reduced in the femoral necks of osteoporosis patients." (PMID 37239124, 2023). "A recent study also found that resveratrol (Res), the SIRT1 agonist, significantly improved bone quality and reduced serum alkaline phosphatase and osteocalcin levels in the rats with osteoporosis." (PMID 36632457, 2023). "In conclusion, SIRT1 plays a positive role in maintaining bone homeostasis, bone mineralization and bone resorption, which also brings hope for the treatment of osteoporosis." (PMID 36632457, 2023). "Sirt1 KO mice presented with osteoporosis characterized by decreased osteogenesis and increased adipogenesis in BMSCs." (PMID 36093072, 2022). "Conversely, SIRT1 transgenic mice are protected against age-induced osteoporosis, and mice treated with SIRT1 agonists show enhanced BMD." (PMID 35267956, 2022). "In summary, quercetin acts as a therapeutic measure for treating aging-related osteoporosis by targeting SIRT1, via antioxidants pathways, thereby inhibits osteoblast apoptosis, autophagy, and inflammatory responses." (PMID 35935939, 2022). "It has been found that resveratrol, as an activator of Sirt1, has obvious antioxidant and anti-aging effects, and significantly inhibits osteoporosis and endothelial cell senescence in rats." (PMID 33562281, 2021). "SIRT1 has been shown to be activated by resveratrol treatment and has also been proved to prevent aging-related diseases such as osteoporosis." (PMID 34572032, 2021). "Accumulating evidence has demonstrated that SIRT1 has a crucial effect in anti-osteoporosis through a complex signaling network, including autophagy and apoptosis." (PMID 34711685, 2021). "In vivo and in vitro, experiments previously showed that SIRT1 promotes resveratrol-treated osteoblasts autophagy to protect against osteoporosis via activating the PI3K-Akt-mTOR signaling pathway." (PMID 34711685, 2021). "Recent studies have shown that Sirt1 also plays an important role in the pathogenesis of osteoporosis, as well as in mesenchymal stem cell differentiation." (PMID 32762716, 2020). "Our findings uncovered a new driver of osteoclastogenesis, the miR-128/SIRT1/NF-κB signaling axis and identified miR-128 as a novel therapeutic target for osteoporosis." (PMID 32292498, 2020).
osteoporosis (continued). "According to another study, highly expressed miR-579-3p in osteoporosis patients regulated Sirtuin 1 (Sirt1) expression." (PMID 32846921, 2020). "Meanwhile, it was verified that treatment with resveratrol markedly increased the BMD in osteoporosis rats, as well as the expression of SIRT1." (PMID 31804494, 2019). "SIRT1 has been shown to be activated by resveratrol treatment, and also has been proved to prevent aging-related diseases such as osteoporosis." (PMID 31804494, 2019). "In fact, Feng and collaborators showed that resveratrol treatment significantly increased the expression of SIRT-1 in a rat model of osteoporosis." (PMID 29862271, 2018). "Most excitingly, pharmacological activation of SIRT1 resulted in significant increases in bone mass in two independent models of osteoporosis." (PMID 28937996, 2017). "Activation of SIRT1 has previously been shown to protect mice against osteoporosis through yet ill-defined mechanisms." (PMID 28542607, 2017). "Ovariectomized female mice and aged male mice, models for post-menopausal and aging-related osteoporosis, respectively, show significant improvements in bone mass upon treatment with SIRT1 agonist, SRT1720." (PMID 28937996, 2017). "Encouragingly, a recent study using a more potent SIRT1 agonist resulted in an even more dramatic rescue in a similar OVX model of osteoporosis." (PMID 28937996, 2017). "Altogether, these findings provide strong evidence that SIRT1 is a positive regulator of bone mass and a promising target for the development of novel therapeutics for osteoporosis." (PMID 28937996, 2017). "Our data solidify SIRT1 as an important regulator of bone mass and promising target for the treatment of osteoporosis." (PMID 28937996, 2017). "To determine the effects of SIRT1 activation on age-related osteoporosis, we treated 12 month old male C57BL/6 mice for 5 months with SIRT1 agonist SRT1720 (100mg/kg/day)." (PMID 28937996, 2017). "Reciprocally, short-term pharmacological activation of SIRT1 in two models of osteoporosis leads to significant increases in bone mass." (PMID 28937996, 2017). "Here we examined the role of SIRT1 in osteoporosis, a classic aging-related disease, by taking a comprehensive in vivo approach." (PMID 28937996, 2017). "Taken together, this suggests that activation of SIRT1 could be a new option for osteoporosis therapy." (PMID 41304967, 2025). "For instance, it remains unclear whether SIRT1 activation has consistent effects on osteoblasts in femur and mandible bone defects and whether the regulatory role of SIRT1 exists in different disease states, such as osteoporosis and inflammation." (PMID 38211965, 2024). "Recent animal studies suggest that SIRT1 could be a valuable pharmacological target for treating osteoporosis and other bone conditions." (PMID 40066121, 2024). "Sirtuin 1 has been identified as an independent protective factor against osteoporosis in T2DM patients and may serve as an earlier indicator of bone metabolism abnormalities than declines in bone mineral density (BMD)." (PMID 39944232, 2024). "Therefore, this review focuses on reviewing the role of SIRT1 in bone metabolism and its impact on osteoporosis, as well as exploring the potential for therapeutic interventions targeting SIRT1." (PMID 39199358, 2024). "Importantly, clinical studies have identified the potential of SIRT1 in predicting and treating related diseases such as osteoporosis and osteonecrosis." (PMID 36632457, 2023). "Furthermore, a study conducted in 2016 confirmed the expression of SIRT1 in the femoral neck region of patients with osteoporosis, thereby validating specific activation of SIRT1 as a potential therapeutic target for treating this condition." (PMID 38264287, 2023). "SIRT1 expression in femoral neck was significantly reduced in patients with osteoporosis." (PMID 36632457, 2023). "The impact of SIRT1 on osteoporosis has been extensively investigated." (PMID 38264287, 2023).
osteoporosis (continued). "Regarding bone health, the inverse relationship between SIRT1 and the bone formation inhibitor sclerostin present in bone tissue and plasma suggests a significant role for SIRT in regulating bone turnover, indicating SIRT1 as a target for the treatment of osteoporosis." (PMID 35956321, 2022). "Previously published data, however, confirm its importance in bone health, as it was shown in a mice knockout model in vivo that miR-146a-5p regulates bone mass via SIRT1, and miR-146a-5p could be considered a therapeutic option for osteoporosis." (PMID 36011354, 2022). "In vivo results showed that resveratrol-mediated SIRT1 and P13k/Akt/mTOR signaling pathways could significantly improve bone quality and protected osteoblasts in rats with osteoporosis." (PMID 36230032, 2022). "It has also been reported that the management of osteoporosis in resveratrol-treated ovariectomized rats could be achieved by activating two signaling pathways—namely, the SIRT1 and wingless-related MMTV integration site (Wnt) pathways." (PMID 35204100, 2022). "In osteoporosis, SIRT1 is activated by resveratrol and subsequently restores the levels of serum markers alkaline phosphatase and osteocalcin by inhibiting the NF-κB signaling pathway, which has a protective effect against osteoporosis." (PMID 36581622, 2022). "A previous study has shown that FA activates SIRT1 to protect against osteoporosis in a rat model." (PMID 34078001, 2021). "Several studies manifested that overexpressing SIRT1 in mesenchymal stem cells facilitates the bone formation of osteoblasts through deacetylation of FoxO3a and inhibition of oxidative stress, thereby alleviating osteoporosis." (PMID 34455406, 2021). "Meanwhile, our findings presented a new visual angle and idea on the mechanism of SIRT1 in osteoporosis, and 17β-E2 combined with SIRT1 might represent a potential therapeutic target for osteoporosis." (PMID 34711685, 2021). "Moreover, RSV promotes skeletal growth through an SIRT1–BMP2 longevity axis and protects osteoblasts by activating the PI3K/Akt/mTOR signaling pathway through enhancing mitophagy, via upregulation of SIRT1 expression in osteoporosis rats." (PMID 34572032, 2021). "In addition, studies have found that H19 mediates estrogen-regulated osteogenic differentiation in BMSCs through the miR-532-3p/SIRT1 axis, and estrogen can mediate miR-532-3p/SIRT1 axis to reduce osteoporosis in ovariectomy rats by up-regulating H19." (PMID 34583640, 2021). "Wen Sun had verified that Sirt1 overexpression promoted FoxO3a deacetylation and inhibited oxidative stress and resisted the apoptosis to increase the osteogenesis and partially restoring the defects of the skeletal system in osteoporosis." (PMID 32967719, 2020). "Resveratrol promotes osteogenesis via activating SIRT1/FoxO1 pathway in osteoporosis mice." (PMID 33708107, 2020). "As the IHC results shown, the expression of osteocalcin and SIRT1 in the osteoporosis group was decreased significantly, while the high-dose resveratrol group significantly increased their expressions when compared with osteoporosis group." (PMID 31804494, 2019). "Moreover, treatment with resveratrol with low-dose or high-dose both increased the protein expression of SIRT1 in the osteoporosis rats." (PMID 31804494, 2019). "Based on experimental data collected in vivo and vitro studies, this study reveals that resveratrol treatment protected osteoblasts in osteoporosis rats by activating the PI3K/Akt/mTOR signaling pathway through enhancing mitophagy via up-regulating the expression of SIRT1." (PMID 31804494, 2019). "The effects of BJ and BE are in part mediated by activity of SIRT1, which has been proposed as a potential target to restore a normal bone remodelling process and for anabolic therapies against excessive bone resorption in osteoporosis." (PMID 31006177, 2019).
osteoporosis (continued). "Our findings on the critical role of SIRT1 in ROS/age‐related perturbations of MSC differentiation capacity highlight this molecule as a target for maintenance of MSC stemness as well as a potential anabolic target in osteoporosis." (PMID 28975701, 2018). "Here we show that pharmacological activation of SIRT1 protects in two models of osteoporosis." (PMID 28937996, 2017). "We next examined the effect of SIRT1 activation in a model of post-menopausal osteoporosis." (PMID 28937996, 2017). "Given that loss of SIRT1 resulted in decreased bone mass, we next explored whether activation of SIRT1 could increase bone mass, particularly in models of osteoporosis." (PMID 28937996, 2017). "The restoration of Sirt1 expression could reveal a possible approach to preventing post-menopausal osteoporosis." (PMID 27529237, 2016). "In addition, SIRT1 has a protective role in glucocorticoid-induced osteoporosis." (PMID 39199358, 2024). "Consequently, this article undertakes a comprehensive examination of the impacts of diverse facets of mitochondrial quality control on osteoporosis, as well as the influence of SIRT1, SIRT3, and SIRT6 on osteoporosis through the regulation of mitochondrial quality control." (PMID 38264287, 2023). "Therefore, we could hypothesize that the up-regulation of SIRT1 induced by 17β-E2 protected against osteoporosis, at least in part, by promoting autophagy via AMPK-mTOR pathway and by inhibiting apoptosis via FOXO3a activation." (PMID 34711685, 2021). "In fact, the increased expression of SIRT1 seems to be related to the osteogenic action of BJ, and these findings confirm that this enzyme may be considered a possible target for anti-resorptive drugs and for anabolic treatments for osteoporosis." (PMID 32024159, 2020). "We therefore have been suggested that SIRT1 involves in oxidative stress‐induced adipogenesis–osteogenesis lineage switching in MSCs, and that targeting this molecule may represent an anabolic therapeutic option for osteoporosis." (PMID 28975701, 2018). "Therefore new SIRT1 agonists, one of which is already in clinical trials, may pave the way towards novel therapeutics for osteoporosis." (PMID 28937996, 2017). "Sirtuin1 (Sirt1), a nicotinamide adenine dinucleotide oxidized (NAD+)-dependent class III deacetylase, regulates the activity of FoxOs, and changes in the levels of Sirt1 expression are associated with the onset of degenerative diseases characterized by increased ROS, including osteoporosis." (PMID 28152064, 2017). "Based on this study, mechanical unloading in disuse osteoporosis downregulates Piezo1 in bone marrow mesenchymal stem cells (BMSCs), impairing calcium influx and disrupting the AMPK/SIRT1 pathway." (PMID 41362723, 2026). "DAAM2 serves as a pivotal downstream effector for SIRT1 to exert immune-regulatory effects in the bone microenvironment; thus, targeting DAAM2 can treat osteoporosis by increasing CD4+ CTL responses." (PMID 40714829, 2025). "Resveratrol prevents cell death and enhances the antioxidant capacity of osteoblasts via activating SIRT1 and deacetylation of FOXO1, thereby mitigating OVX-induced osteoporosis." (PMID 40153585, 2025). "Specifically, resveratrol treatment dose-dependently increases SIRT1 expression in osteoblasts and significantly improves BMD in animal models of osteoporosis." (PMID 40956314, 2025). "This study demonstrates that serum Sirtuin 1 levels are significantly lower in T2DM patients compared to non-diabetic controls, with an even greater reduction observed in those with osteoporosis." (PMID 39944232, 2024). "This study investigates the relationship between Sirtuin 1 levels, BMD, and bone metabolism in newly diagnosed T2DM patients, specifically examining alterations in Sirtuin 1 levels in those with concomitant osteoporosis or osteopenia." (PMID 39944232, 2024).